MTOR (mechanistic target of rapamycin kinase)
Diseases named in the same sentence as MTOR in open-access papers (continued):
Sharing a sentence is not in itself a finding about the gene and the disease.
schizophrenia (continued). "Autopsy studies of the brains of schizophrenia patients have revealed the presence of inclusions in neurons that may occur due to the dysfunction in mTOR-related cellular clearance systems." (PMID 36430976, 2022). "In addition to its coupling to Gs protein, the 5-HT6 receptor also engages mTOR signaling to compromise cognition in neurodevelopmental models of schizophrenia and preclinical models of cannabis abuse during adolescence and neuropathic pain." (PMID 34576341, 2021). "In summary, the mTOR signaling pathway is involved in the downstream signal transduction mechanism of genes related to schizophrenia, in alterations in synaptic plasticity and cognitive functions, and in the mechanism of extrapyramidal adverse reactions to antipsychotic drugs." (PMID 34348681, 2021). "However, to date, little is known about the gene expression profile of the mTOR pathway in patients with schizophrenia." (PMID 34348681, 2021). "More recently a new hypothesis for schizophrenia aetiology has arisen; the mammalian target of rapamycin (mTOR) hypothesis." (PMID 34366935, 2021). "Recent research has indicated that the mammalian target of rapamycin protein (mTOR) pathway may be involved in schizophrenia pathogenesis." (PMID 34348681, 2021). "This study examined the expression levels of mTOR pathway genes in patients with schizophrenia before and after olanzapine treatment, which is very important to further understand the pathological changes in the mTOR pathway related to schizophrenia." (PMID 34348681, 2021). "Their study sheds further light on the role of mTOR in Schizophrenia and could inform the development of future therapeutic strategies for the condition." (PMID 34112930, 2021). "Based on these studies, the MTOR gene may be abnormally expressed in patients with schizophrenia and other psychiatric disorders." (PMID 34348681, 2021). "Abnormalities in the mTOR pathway, especially DEPTOR and mTORC2, might play important roles in the autophagy mechanism underlying the pathophysiology of schizophrenia and effects of olanzapine treatment." (PMID 34348681, 2021). "The mammalian target of rapamycin protein (mTOR) signaling pathway is involved in the pathogenesis of schizophrenia and the mechanism of extrapyramidal adverse reactions to antipsychotic drugs, which might be mediated by an mTOR-dependent autophagy impairment." (PMID 34348681, 2021). "Inhibition of either PI3K/PKB or mTOR leads to inhibited of neuronal growth and thus might contribute to the aberrant synaptic architecture seen in schizophrenia." (PMID 34366935, 2021). "Interestingly, chronic THC exposure during adolescence induces schizophrenia-like behaviors and decreases mTOR-p70S6K signaling pathway in the PFC of adult rat brains." (PMID 32265715, 2020). "Recent studies suggest that mTOR signaling pathway dysfunction could be involved in the etiopathogenesis of schizophrenia." (PMID 32265715, 2020). "Moreover, it has been demonstrated that NRG1 also regulates DISC1 expression, thus further worsening the aberrancy of the Akt–mTOR pathway and the pathogenesis of schizophrenia and related behaviors." (PMID 30061532, 2018). "As briefly reported, despite a high number of studies correlating mTOR and autophagy with neurological disorders, only a few studies addressed such an issue in psychiatric disorders such as schizophrenia." (PMID 30061532, 2018). "The mTOR has a role mediated by Wnt signaling pathway in the neuropathology of schizophrenia." (PMID 28117656, 2016). "The upstream signaling pathways concerned with translational control of protein synthesis are eIF2 and mTOR signaling, and we observed these pathways to be dysregulated in schizophrenia patient-derived ONS and iPSC models, and at the level of the genome in schizophrenia population-based data." (PMID 26485547, 2015). "The AKT/mTOR signaling cascade may play a significant role in the pathogenesis of schizophrenia." (PMID 41283305, 2025).
schizophrenia (continued). "One of the most recent findings that may underlie the mechanism of schizophrenia development is the hypofunction of ribosomal protein S6 in the prefrontal cortex of patients with schizophrenia, which is an effector of the mTOR pathway and plays an important role in regulating protein synthesis." (PMID 40566484, 2025). "However, the role of the PI3K/AKT/mTOR signaling pathway in schizophrenia remains controversial." (PMID 38365306, 2024). "In addition, the 5′‐UTR of DPYSL2 interacts with mTOR effectors in schizophrenia." (PMID 36621846, 2023). "Additionally, we found that many of the signaling pathways, such as G-Protein Signaling, mTOR signalling, MAPK Signaling pathway and those pathways are associated with at least one of the brain disorder: autism spectrum disorder, schizophrenia, and bipolar disorder." (PMID 34078267, 2021). "Nevertheless, this study is a promotion to understand the role of mTOR pathway in autophagy mechanism of patients with schizophrenia, and to explore whether these genes are potential biomarkers for the diagnosis of and determination of therapeutic efficacy in patients with schizophrenia." (PMID 34348681, 2021). "The mTOR signaling pathway might be involved in the pathogenesis of schizophrenia." (PMID 34348681, 2021). "The mTOR pathway controlling neurogenesis, synaptogenesis, cell proliferation, autophagy, and apoptosis, becomes a very important signaling pathway, whose disorder leads to serious consequences and is considered an important etiological factor of schizophrenia." (PMID 32121669, 2020). "Notably, pharmacological treatment with antipsychotics leads to increased pathway activation in mouse and cell-based models of schizophrenia, and in the latter study, the antipsychotic haloperidol also increased dendritic spine density in an mTOR-dependent manner." (PMID 31548888, 2019). "Interestingly, as has emerged from review of the literature published in the last few years, a novel scenario begins to delineate in which a dysfunctional mTOR pathway may be a key mechanism in the chain of events for the development of schizophrenia." (PMID 30061532, 2018). "Thus, in the next paragraph we discuss evidence on how altered mTOR and an impaired autophagy pathway may indeed represent a common hub between drug addiction and schizophrenia." (PMID 30061532, 2018). "Analysis in schizophrenia genome-wide association data from the Psychiatric Genetics Consortium specifically implicated eIF2α regulatory kinase EIF2AK2, and confirmed the importance of the eIF2α, eIF4 and mTOR translational control pathways at the level of the genome." (PMID 26485547, 2015). "However, the disruption of mTOR activity may result in the development of schizophrenia." (PMID 38365306, 2024). "In animal models of simulated schizophrenia, enhanced phosphorylation levels of PI3K, Akt, and mTOR relieved abnormalities in schizophrenia-like behaviors in rodents." (PMID 38365306, 2024). "Among the overlapping modules, we identified one mTOR/EIF2 signaling module, which contained genes from all the sets of the placental schizophrenia TWASs (19 from set1: whole sample TWAS, 15 from set2: female TWAS, 18 from set 3: male TWAS)." (PMID 37188697, 2023). "The MTOR and RICTOR mRNA expression levels in patients with acute schizophrenia were significantly decreased compared with those of healthy controls and further significantly decreased after four weeks of olanzapine treatment." (PMID 34348681, 2021). "Misregulation of mTOR via upstream proteins phospotidylinositol 3-phosphate kinase (PI3K) and protein kinase B (PKB) is thought to contribute to schizophrenia." (PMID 34366935, 2021). "Moreover, these compounds may possess other mechanisms, such as antioxidant and mechanistic target of rapamycin (mTOR) effects, which are involved in many aspects of memory and cognition in the healthy human brain, as well as in the brains of patients with schizophrenia." (PMID 34575878, 2021).
schizophrenia (continued). "In such an attempt, we hint to the role of mTOR-dependent autophagy as a hub in etiologically distinct brain disorders from neurodegeneration to METH abuse and schizophrenia." (PMID 30061532, 2018). "However, regarding the level of PI3K, AKT, mTOR, GSK3-α and GSK3-β in peripheral mononuclear cells (PMCs), the results are contradictory, possibly due to the heterogeneity of schizophrenia." (PMID 41283305, 2025). "In addition, 11-oxo-mogrol regulates schizophrenia by reversing MK801-induced inactivation of AKT and phosphorylation of mammalian target of rapamycin (mTOR)." (PMID 38638866, 2024). "To date, relatively few studies have examined the effects of mTOR signaling on the positive and negative symptoms of schizophrenia." (PMID 38365306, 2024). "Similarly, in a rat model of induced schizophrenia, mTOR signalling is reduced, whereas CBD treatment increased mTOR activity and reversed symptoms." (PMID 33347604, 2021). "The downregulation of Akt/mTOR signaling proteins in postmortem PFC of SZs, together with postmortem studies showing that spine density is reduced in the cortex of schizophrenia patients further support our results." (PMID 32265715, 2020). "In addition, we found that inhibition of Akt/mTOR pathway by rapamycin blocks the changes in 5-HT2AR signaling pattern and the supersensitivity to schizophrenia-like effects induced by chronic THC." (PMID 29748632, 2018). "Nrg1α-induced PI3K signaling is also impaired in lymphoblastoid cell lines derived from schizophrenia patients, suggesting PI3K-Akt-mTOR signaling in response to Nrg1 may be impaired in schizophrenia in a manner that mirrors the effects of reduced miR-137." (PMID 30618607, 2018). "Therefore, the aim of the present manuscript is to mention the role of mTOR-dependent autophagy in neurodegeneration while emphasizing its role in methamphetamine (METH) addiction and psychiatric disorders, namely schizophrenia." (PMID 30061532, 2018). "To go through this hypothesis, we quantified the protein expression and phosphorylation of the mTOR downstream effector ribosomal protein S6 as well as other pathway interactors such as Akt and GSK3β, in postmortem PFC from subjects with schizophrenia and control subjects." (PMID 32265715, 2020). "Regarding the role of Rhes in psychiatric disorders, the work of Liu and colleagues demonstrated that Rhes may be a potential vulnerability factor for schizophrenia, whereas Rhes was also found to influence schizophrenia-related transduction pathways within the STR, such as of Akt and mTOR." (PMID 30925704, 2019). "Furthermore, the mTOR pathway, which is modulated by rapamycin treatment, is a novel drug target for the treatment of ASD, schizophrenia and affective disorders." (PMID 28775826, 2017).
clear cell renal cell carcinoma (68 papers, 2012 to 2026). "Furthermore, mTOR inhibitors have proven effective in the treatment of clear renal cell carcinoma, a cancer associated with loss of pVHL function and deregulation of hypoxia pathways." (PMID 32245394, 2020). "Besides, 6% of clear-cell renal cell carcinoma patients with mTOR mutation were identified." (PMID 35402264, 2022). "We analyzed the data from a study, where clear renal cell carcinoma patients were treated with either nivolumab, a PD-1 blockade therapy, or everolimus, an mTOR inhibitor." (PMID 40522999, 2025). "HIF1A-HIF2A, mTOR, CD27-CD70, CTLA4, PD-1, PD-L1, and PD-L2 are important biomarkers linked to drug resistance in metastatic Clear Cell Renal Cell Carcinoma (ccRCC)." (PMID 39796121, 2024). "CD105+ Kidney CSCs derive from nephron progenitors in clear cell renal carcinoma and confer radioresistance via mTOR and Chk1 signaling." (PMID 38800385, 2024). "We sought to identify mTOR-phosphorylated proteins that are differently expressed in clinically resected clear cell renal cell carcinoma (ccRCC) relative to pair-matched normal renal tissue." (PMID 37298315, 2023). "It regulates the transcription of PDGFB to activate the mTOR signaling pathway, thereby regulating lipid metabolism to promote the progression of renal clear cell carcinoma." (PMID 37391422, 2023). "In the case of renal clear cell carcinoma, patients often develop resistance to mTOR inhibitors everolimus and temsirolimus." (PMID 35495621, 2022). "Papillary (ACHN), clear cell renal cell carcinoma (786-O), and the immortalized human proximal tubular epithelial cell line (HK-2) exhibited similar p-mTOR levels that indicate a significant mTOR kinase activity in all the studied cells." (PMID 36142502, 2022). "A novel path for targeted treatment of renal clear cell carcinoma has emerged due to VEGF mutations and aberrant PI3K/AKT/mTOR signaling." (PMID 35389815, 2022). "A Western blot assay was conducted to further investigate LTB4R’s effect on apoptosis, cell cycle, EMT process, and AKT/mTOR signaling pathway in renal clear cell carcinoma at the protein level." (PMID 36429034, 2022). "The mTOR inhibitor everolimus is used alone or as part of chemotherapeutics regimens in breast cancer, renal clear cell carcinoma, subependymal giant cell astrocytoma, and advanced neuroendocrine tumors." (PMID 35495621, 2022). "Clear-cell renal cell carcinoma is highly infiltrated with T cells, and therapeutic interventions such as the use of MTOR inhibitors and checkpoint inhibitors (PD-1 and PD-L1) have been shown to be effective in the management of ccRCC." (PMID 34439859, 2021). "Resistance to the mechanistic target of rapamycin (mTOR) inhibitors, which are a standard treatment for advanced clear cell renal cell carcinoma (ccRCC), eventually develops in most cases." (PMID 33107222, 2021). "Specifically, a recurrent event in clear-cell renal cell carcinoma (ccRCC) is the hyperactivation of the mTOR signaling that promotes oncogenic metabolic programs." (PMID 34179848, 2021). "Increased cytoplasmic lipid droplets (LDs) and elevated AKT/mTOR signaling are characteristics of clear cell renal cell carcinoma (ccRCC)." (PMID 32492043, 2020). "Chromosomal rearrangements are common in clear cell renal cell carcinoma (ccRCC) and their roles in mediating sensitivity to tyrosine kinase inhibitors (TKIs) and mTOR inhibitors (mTORi) remain elusive." (PMID 32628820, 2020). "PTEN and PIK3CA are associated with the PI3K/mTOR pathway, which is a target for the mTOR inhibitor, everolimus, now approved in renal clear cell carcinoma." (PMID 31795195, 2019). "Molecular targeted drugs inhibiting vascular endothelial growth factor (VEGF) or mammalian target of rapamycin (mTOR) have been widely used for patients with metastatic or recurrent clear cell renal cell carcinoma (ccRCC)." (PMID 29796168, 2018).
clear cell renal cell carcinoma (continued). "Mammalian target of rapamycin (mTOR) is critical for cellular growth, proliferation, and angiogenesis in clear cell renal carcinoma." (PMID 27453754, 2016). "In human clear cell renal carcinomas (ccRCC), the phosphoinositide 3-kinase (PI3K)/protein kinase B (AKT)/mammalian target of rapamycin (mTOR) cascade is frequently mutated and activated." (PMID 25948777, 2015). "Additionally, the inhibition of PLK1, a cell-cycle-related kinase, has been identified as a potential therapeutic target in clear cell renal cell carcinoma, further supporting the potential of combined mTOR and Chk1 inhibition in this context." (PMID 38800385, 2024). "Furthermore, PIK3CA mutations and increased mTOR signalling have been linked to poor response to ICB in other cancer types, including breast, colorectal and clear cell renal cancer." (PMID 38711203, 2024). "To verify the relationship between LTB4R and the AKT/mTOR signaling pathway in renal clear cell carcinoma, we performed a Western blot assay and found that LTB4R positively regulates the AKT/mTOR pathway, affecting the development of renal clear cell carcinoma." (PMID 36429034, 2022). "In addition, we found that LTB4R regulated the proliferation and apoptosis of renal clear cell carcinoma cells by regulating the AKT/mTOR signaling pathway’s phosphorylation process." (PMID 36429034, 2022). "Despite advances in the treatment of patients with advanced clear-cell renal cell carcinoma (ccRCC) with anti-angiogenic agents, checkpoint inhibitors, and mammalian target of rapamycin (mTOR) inhibitors alone and in combination, durable responses are seen in about 30% of treated ccRCC patients." (PMID 30380599, 2018). "Case 1 had clear cell renal carcinoma and underwent nephrectomy; he then received several lines of tyrosine kinase inhibitor directed against vascular endothelial growth factor receptors and the mTor complex." (PMID 30474572, 2018). "A number of treatments targeting VEGF or mTOR pathways have been approved for metastatic clear cell Renal Cell Carcinoma (ccRCC), but the majority of patients show disease progression after first line therapy with a very low rate of complete or long-term responders." (PMID 27738339, 2016). "Using publicly available tumor genome sequencing data, we identified several point mutations in MTOR and its upstream regulator RHEB (Ras homolog enriched in brain) in patients with clear cell renal cell carcinoma (ccRCC), the most common histology of kidney cancer." (PMID 26255626, 2015). "In this case report, we present the case of a 61-year-old man with clear cell renal cell carcinoma who underwent targeted therapy with the receptor tyrosine kinase (RTK) inhibitor lenvatinib and the mammalian target of rapamycin (mTOR) inhibitor everolimus." (PMID 38023618, 2023). "Clear cell renal cell carcinoma (ccRCC) is a hypervascular tumor that is characterized by bi-allelic inactivation of the VHL tumor suppressor gene and mTOR signalling pathway hyperactivation." (PMID 37047421, 2023). "Before the introduction of the more recent immunologic therapies for metastatic clear cell renal carcinoma (metastatic CCRC), antiangiogenic and anti-mammalian target of rapamycin (mTOR) agents represented the cornerstone of treatment for over 10 years." (PMID 34885006, 2021). "In clear cell renal cell carcinoma, TP73-AS1 silencing suppressed cell proliferation and promoted apoptosis in vitro through the upregulation of KISS1 expression and the activation of PI3K/Akt/mTOR signaling." (PMID 35614413, 2022).
clear cell renal cell carcinoma (continued). "Although mTOR inhibitors have been approved as first-line therapy for treating metastatic clear cell renal cell carcinoma (ccRCC), the lack of useful markers reduces their therapeutic effectiveness." (PMID 32235551, 2020). "In the kidney, p-mTOR staining was negative or focally positive in clear cell renal cell carcinoma (RCC), while p-mTOR staining was strong in metastatic RCC." (PMID 28831205, 2017). "Kinase inhibitors targeting vascular endothelial growth factor receptors (VEGFR) and mammalian target of rapamycin (mTOR) improve outcomes in metastatic clear cell renal cell carcinoma (ccRCC), but are not curative." (PMID 27574806, 2016).